UNCX (UNC homeobox)
Description:
Transcription factor involved in somitogenesis and neurogenesis. Required for the maintenance and differentiation of particular elements of the axial skeleton. May act upstream of PAX9. Plays a role in controlling the development of connections of hypothalamic neurons to pituitary elements, allowing central neurons to reach the peripheral blood circulation and to deliver hormones for control of peripheral functions (By similarity).
Synonyms: UNCX4.1
Tractability: No criterion of Open Targets' tractability assessment is met for any kind of drug.
Gene: Protein-coding gene on chromosome 7 (1,232,872 to 1,237,326, forward strand). Ensembl gene ENSG00000164853.
Subcellular location: Nucleus
Subcellular location (Human Protein Atlas): Nucleoplasm
Gene Ontology:
Molecular function: sequence-specific double-stranded DNA binding; DNA-binding transcription factor activity, RNA polymerase II-specific; DNA binding
Biological process: regulation of gene expression; regulation of DNA-templated transcription; regulation of transcription by RNA polymerase II
Cellular component: chromatin; nucleus
Genetic constraint (gnomAD): Loss-of-function variants: 4 observed, 8.27 expected, observed/expected ratio (o/e) 0.48, 90% interval 0.24 to 1.11. That is too few expected variants to judge how well the gene tolerates losing a copy. Missense variants: 749 observed, 546.13 expected, observed/expected ratio (o/e) 1.37, 90% interval 1.29 to 1.46. Synonymous variants: 459 observed, 286.55 expected, observed/expected ratio (o/e) 1.6, 90% interval 1.48 to 1.73.
Homologues: Orthologues: chimpanzee UNCX (100% identical), pig UNCX (90% identical), dog UNCX (89% identical), mouse Uncx (88% identical), rat Uncx (88% identical), guinea pig UNCX (71% identical), tropical clawed frog uncx (54% identical), zebrafish uncx (48% identical), zebrafish uncx4.1 (47% identical), macaque UNCX (30% identical). Paralogues in human: ARX (18% identical), ALX4 (17% identical), PAX7 (16% identical), ALX3 (15% identical), VSX2 (15% identical), RAX (15% identical), PHOX2A (14% identical), SHOX (14% identical), OTP (14% identical), PHOX2B (14% identical), SHOX2 (14% identical), OTX1 (14% identical), and 38 more.
Diseases named in the same sentence as UNCX in open-access papers:
UNCX is named in the same sentence as 7 diseases in open-access papers, as found by Europe PMC text mining. Sharing a sentence is not in itself a finding about the gene and the disease. The quoted sentences say what the papers report.
diabetes (1 paper, 2016). "The previously identified UMOD locus showed genome-wide significant association with eGFRcrea among those with diabetes (rs12917707, P value=2.5 × 10−8), and six loci (NFKB1, UNCX, TSPAN9, AP5B1, SIPA1L3 and PTPRO) had nominally significant associations with eGFRcrea among those with diabetes." (PMID 26831199, 2016).
Pleural effusion (1 paper, 2021). The presence of an excessive amount of fluid in the pleural cavity. "Interestingly, Ooki and colleagues, determined the clinical utility of a set of six genes, including CDO1, HOXA9, AJAP1, PTGDR, UNCX, and MARCH11, for predicting LC diagnosis not only in serum samples but also in pleural effusions and ascites." (PMID 33937034, 2021).
small cell lung carcinoma (1 paper, 2024). Small cell lung cancer (SCLC) is a highly aggressive malignant neoplasm, accounting for 10-15% of lung cancer cases, characterized byrapid growth, and early metastasis. "Interestingly, copy number gains involving this genomic region known to harbor oncogenes such as UNCX, FAM20C, MAD1L1 and PDGFA have been reported during the immortalization process of patient-derived small cell lung cancer lines." (PMID 39737401, 2024).
tumor (2 papers, 2022 to 2023). "The genes expression levels in the model were detected by qRT-PCR, and the results showed that they were highly expressed in 20 pairs of tumor and normal tissues (UNCX, SLC6A3, AGAP2-AS1, LINC00968, PTX3 and SBSPON), while ITPRID1, DCST2, ETV3L, and ENSG00000261327 were down-regulated." (PMID 36647156, 2023).
cancer (1 paper, 2024). A tumor composed of atypical neoplastic, often pleomorphic cells that invade other tissues. "Previous studies have determined a direct role for the SS18-SSX fusion protein in regulating expression of several cancer-related genes, such as EGR1, FOS, IGF2, FZD10, SOX2, UNCX and CDH4." (PMID 39045458, 2024).
UNCX also shares sentences with these, for which no sentence is quoted: Intellectual disability (1 paper); ischemic stroke (1).